ZRSR2 (zinc finger CCCH-type, RNA binding motif and serine/arginine rich 2)
Diseases named in the same sentence as ZRSR2 in open-access papers:
ZRSR2 is named in the same sentence as 40 diseases in open-access papers, as found by Europe PMC text mining. Sharing a sentence is not in itself a finding about the gene and the disease. The quoted sentences say what the papers report.
myelodysplastic syndrome (25 papers, 2015 to 2025). A clonal hematopoietic disorder characterized by dysplasia and ineffective hematopoiesis in one or more of the hematopoietic cell lines. "Such mutations, including hotspots in SF3B1 and U2AF1 and loss-of-function events in FUBP1, RBM5, RBM10, and ZRSR2, are recurrent in myelodysplastic syndromes, acute myeloid leukemia, chronic myelomonocytic leukemia, and multiple solid tumors 8,42–45." (PMID 41279721, 2025). "Spliceosome mutations, such as those in SF3B1, SRSF2, U2AF1, and ZRSR2, are commonly found in myeloid neoplasms like myelodysplastic syndromes (MDSs) and other MPNs." (PMID 40507313, 2025). "Due to the aberrant splicing of LZTR1 (leucine zipper-like transcriptional regulator 1), mutations in the splicing factor ZRSR2 have been associated with a number of illnesses, including myelodysplastic syndromes (MDS) and predispositions to cancer." (PMID 39584923, 2024). "Recurrent somatic mutations of the SFG, such as SF3B1, SRSF2, U2AF1, and ZRSR2, have been uncovered in myelodysplastic syndrome (MDS), chronic lymphocytic leukemia, acute myeloid leukemia, breast cancer, lung adenocarcinoma, and uveal melanoma." (PMID 36684432, 2022). "One such is the zinc-finger-RNA-binding-motif-and-serine/arginine-rich-2 (ZRSR2), which is clinically implicated in myelodysplastic syndrome and leukemia." (PMID 35371815, 2022). "Recent sequencing studies have identified frequent somatic ZRSR2 mutations in hematological malignancies, such as myelodysplastic syndrome (MDS), causing mis-splicing of U12 introns." (PMID 32527007, 2020). "Various sequencing studies have identified somatic ZRSR2 mutations in hematological diseases, such as myelodysplastic syndrome (MDS), chronic lymphocytic leukemia (CLL), chronic myelomonocytic leukemia (CMML), or thyroid cancer." (PMID 39907312, 2025). "For comparison, we carried out the same analysis on a previously published dataset derived from myelodysplastic syndrome (MDS) patients carrying somatic mutations in the gene encoding for the U11/12‐di‐snRNP subunit ZRSR2 (Madan et␣al,2015)." (PMID 34009673, 2021). "ZRSR2 is frequently mutated in myeloid malignancies and in ~5% of patients with myelodysplastic syndromes (MDS)." (PMID 33568749, 2021). "The human ZRSR2 gene is localized on the X chromosome, and somatic loss-of-function mutations in ZRSR2 are reported in ∼5% of patients with myelodysplastic syndrome (MDS)." (PMID 36142581, 2022). "Mutations in LUC7L2, PRPF8,SF3B1, SRSF2, U2AF1, and ZRSR2 genes occur at various frequencies ranging between 40% and 85% in different subtypes of myelodysplastic syndrome (MDS) and 5% and 10% of acute myeloid leukemia (AML) and myeloproliferative neoplasms (MPNs)." (PMID 31766606, 2019). "Mutations of ZRSR2, a gene involved in RNA splicing, are not closely associated with mast cell disorders, but rather with myelodysplastic syndromes development." (PMID 41440762, 2025). "Mutations in RNA splicing factor genes including SF3B1, U2AF1, SRSF2, and ZRSR2 have been reported to contribute to development of myeloid neoplasms including myelodysplastic syndrome (MDS) and secondary acute myeloid leukemia (sAML)." (PMID 38883705, 2024). "Genes of the spliceosome-complex including SRSF2, SF3B1, U2AF1, and ZRSR2 are frequently mutated in myeloid malignancies such as AML, myelodysplastic syndromes (MDS) or myeloproliferative disorders." (PMID 33692956, 2021). "In contrast, mutations of ZRSR2, a gene involved in RNA splicing, are not closely associated with mast cell disorders, but rather with myelodysplastic syndromes (MDS) development." (PMID 41440762, 2025).
Myelodysplasia (10 papers, 2022 to 2025). Clonal hematopoietic stem cell disorders characterized by dysplasia (ineffective production) in one or more hematopoietic cell lineages, leading to anemia and cytopenia. "Altogether, Zrsr2 and Tet2 mutations cause a phenotype that recapitulates critical features of myelodysplasia." (PMID 36030305, 2022). "In particular, the adverse-risk group has been expanded to include seven additional mutations: BCOR, EZH2, SF3B1, SRSF2, STAG2, U2AF1, and ZRSR2—together with ASXL1 and RUNX1 (already included in ELN 2017)—forming the “myelodysplasia-related” (MR) gene group." (PMID 41464583, 2025). "Males had a higher frequency of mutations in genes of the spliceosome complex (SF3B1, SRSF2, U2AF1 or ZRSR2) (19.1% vs. 5.7% in females; P = 0.002) and the nine myelodysplasia-related genes (31.6% vs. 17.9% in females; P = 0.015)." (PMID 38890297, 2024). "The presence of mutations in at least one gene associated with myelodysplasia (i.e., SRSF2, SF3B1, U2AF1, ZRSR2, ASXL1, EZH2, BCOR, or STAG2) was significantly more frequent in older patients." (PMID 35805006, 2022). "Seventy-nine patients, or 45% of all re-classified patients, were moved from ELN-2017 favorable (n = 11) or intermediate (n = 68) to ELN-2022 adverse risk based on the inclusion of additional myelodysplasia-related (MR) mutations (BCOR, EZH2, SF3B1, SRSF2, STAG2, U2AF1, ZRSR2) as poor-risk markers." (PMID 37041198, 2023).
myeloid neoplasm (10 papers, 2021 to 2025). Proliferation of myeloid cells originating from a primitive stem cell. "Murine models with conditional heterozygous expression of splicing factor (SF) mutations (SF3B1, U2AF1, SRSF2, ZRSR2) have confirmed the causative effects of RNA splicing dysregulation in the pathogenesis of myeloid malignancies and CLL." (PMID 37463047, 2023). "Pathogenic variants specific for MDS‐type myeloid neoplasms were found by NGS in the NRAS, U2AF1 and ZRSR2 genes with VAFs of 40%, 24% and 6%, respectively." (PMID 40066790, 2025). "In addition, mutations of ZRSR2 are not reported to be implicated in mastocytosis, whereas they occur in other myeloid neoplasms, such as MDS." (PMID 41440762, 2025).
chronic myelomonocytic leukemia (8 papers, 2012 to 2025). A myelodysplastic/myeloproliferative neoplasm which is characterized by persistent monocytosis, absence of a Philadelphia chromosome and BCR/ABL fusion gene, fewer than 20 percent blasts in the bone marrow and blood, myelodysplasia, and absence of PDGFRA or PDGFRB rearrangement. "Multiple types of mutations in ZRSR2 have been observed in chronic myelomonocytic leukemia and chronic lymphocytic leukemia." (PMID 36251702, 2022). "Apart from MDS, ZRSR2 mutations have also been reported in other hematological malignancies including chronic myelomonocytic leukemia (CMML), myeloproliferative neoplasms (MPN), and blastic plasmacytoid dendritic cell neoplasm (BPCDN)." (PMID 36030305, 2022). "SRSF2, ZRSR2, and U2AF1 mutations show frequencies of ∼8–30% in chronic myelomonocytic leukaemia (CMML) and MDS-RS patients." (PMID 23056961, 2012). "Finally, for comparison, in the analysed articles, around 33% of chronic myelomonocytic leukemia (CMML) patients harbored SRSF2 mutations; 8% U2AF1 mutations, 9% ZRSR2 mutations and 5%, SF3B1 mutations." (PMID 32784800, 2020).
breast carcinoma (3 papers, 2019 to 2022). "On average, ZRSR2 mutations are found in 1.2% of all cancers; the most common types are lung cancer, breast cancer, colon cancer, and ovarian cancer." (PMID 36251702, 2022).
chronic lymphocytic leukemia (3 papers, 2016 to 2022). "Alterations in SF3B1 were initially discovered in myelodysplastic syndromes (MDSs) and chronic lymphocytic leukemia (CLL), together with other mutations of splicing factors, such as U2AF1, SRSF2 and ZRSR2 (refs 1, 2, 3)." (PMID 26842708, 2016). "Patients with MDS, chronic myelomonocytoic leukemia (CMML), or chronic lymphocytic leukemia (CLL) acquire mutations in the spliceosomal components SF3B1, SF1, PRPF40B, and U2AF35 besides mutations in the splicing factor SRSF2 and ZRSR2, a component of U11/U12 di-snRNP." (PMID 30246013, 2018).
leukemia (3 papers, 2021 to 2023). A malignant (clonal) hematologic disorder, involving hematopoietic stem cells and characterized by the presence of primitive or atypical myeloid or lymphoid cells in the bone marrow and the blood. "As ZRSR2 is located on the X chromosome, mutations are linked to male-predominant leukemia—particularly in blastic plasmacytoid dendritic cell neoplasm." (PMID 37444402, 2023). "Additionally, leukemia cells with ZRSR2 knockdown exhibited slower growth compared with wild-type controls, a pattern not exclusive to loss of ZRSR2; U2AF1mut AML demonstrated similar findings of reduced hematopoietic reconstitution." (PMID 37444402, 2023).
lung cancer (3 papers, 2021 to 2025). A malignant neoplasm involving the lung. "Based on these findings, we hypothesize that missense mutations in NTRK1 and ZRSR2 may contribute to primary resistance to Osimertinib in non‐small cell lung cancer (NSCLC) with EGFR mutations through modulation of the PI3K pathway." (PMID 39907312, 2025). "Here, we present the initial instance of a non‐small cell lung cancer (NSCLC) patient with an EGFR mutation who also harbored both NTRK1 and ZRSR2 mutations, which are recognized as significant factors in the development of primary resistance to Osimertinib through further validation." (PMID 39907312, 2025).
colon cancer (2 papers, 2022). "In the setting of aplastic anemia and lynch negative colon cancer, we suspect our patient could have aplastic anemia due to an autoimmune phenomenon, underlying common variable immunodeficiency disease (CVID), or the new ZRSR2 mutation could be playing a role." (PMID 35371815, 2022).
macrocytic anemia (2 papers, 2019 to 2022). Anemia that is characterized by increased red blood cell volume. "However, old Zrsr2m/m mice did display several hematological alterations, such as reduced RBC and hemoglobin levels akin to patients with isolated ZRSR2 mutations showing refractory macrocytic anemias." (PMID 36030305, 2022).
Thrombocytopenia (2 papers, 2022). A reduction in the number of circulating thrombocytes. "Here we show that mutations of Zrsr2 and Tet2, genes commonly co-mutated in human MDS, resulted in impairment of myelo-erythroid differentiation and the development of thrombocytopenia and anemia, multi-lineage dysplasia, and splenomegaly with extramedullary hematopoiesis." (PMID 36030305, 2022).
acute leukemia (1 paper, 2025). A clonal (malignant) hematopoietic disorder with an acute onset, affecting the bone marrow and the peripheral blood. "Co-mutations varied by subtype; MDS/MPN, NOS, and CMML cases frequently harbored mutations in epigenetic regulators (ASXL1, TET2) and splicing factors (SF3B1, SRSF2, ZRSR2), while acute leukemia cases showed alterations in JAK3, STAT3, and NRAS." (PMID 40806796, 2025).
adenocarcinoma of the colon (1 paper, 2022). "Here, we present a case of a young male with myriad autoimmune conditions and adenocarcinoma of the colon in the setting of ZRSR2 mutation." (PMID 35371815, 2022).
bladder cancer (1 paper, 2020). "We first downloaded the mRNA expression data of normal and bladder cancer tissues from TCGA database and analyzed the mRNA expression of a total of 97 RNA splicing proteins (including SRSF family, RBM family, HNRNP family, SF3B1, PRMT5, PUF60, U2AF1, and ZRSR2) between normal and carcinoma tissues." (PMID 33117697, 2020).
essential thrombocythemia (1 paper, 2020). A chronic myeloproliferative neoplasm that involves primarily the megakaryocytic lineage. "Thirteen genes including ASXL1, U2AF1, SRSF2, SF3B1, and ZRSR2 had significantly higher mutation frequencies in primary myelofibrosis (PMF) compared with essential thrombocythemia and polycythemia vera; this difference distinguished PMF from MPN and likened it to MDS." (PMID 33117717, 2020).
Fanconi Anaemia (1 paper, 2025). "Here, the authors find EXO1 loss as synthetic lethal with many DDR genes involved in various cancers, including genes from Fanconi Anaemia pathway, BRCA1-A complex, and spliceosome factor ZRSR2; such interactions represent potential clinical targets." (PMID 41006228, 2025).
Hepatic steatosis (1 paper, 2025). Steatosis is a term used to denote lipid accumulation within hepatocytes. "Depletion of Zrsr1 and Zrsr2, two essential minor intron splicing factors in the liver, directly induced hepatic steatosis and further promoted MASH progression upon obesity-induced insulin resistance and LXR activation." (PMID 40100939, 2025). "Second, mice with hepatic Zrsr1 and Zrsr2 depletion exhibited spontaneous hepatic steatosis and fibrosis phenotypes that were independent of dietary conditions." (PMID 40100939, 2025).
Iron overload (1 paper, 2025). "Iron overload can lead to genomic and chromosomal instability, with a significant reduction in the ZRSR2 gene mutation and increased incidence of 7q- chromosomal abnormalities in IOL MDS patients." (PMID 40635108, 2025).
myocardial infarction (1 paper, 2023). Gross necrosis of the myocardium, as a result of interruption of the blood supply to the area, as in coronary thrombosis. "In the first patient (male ET) who suffered from myocardial infarction at follow-up, we detected ZRSR2 p.Ser447_Arg448dup c.1338_1343dup variant at high VAF (ranging 84,78% - 84,38% between samples), which is suspected to increase the risk of thrombosis." (PMID 37671053, 2023).
cancer (16 papers, 2020 to 2026). A tumor composed of atypical neoplastic, often pleomorphic cells that invade other tissues. "ZRSR2 mutations are linked to a process known as minor intron retention, which is responsible for several cancer predispositions and MDS." (PMID 39584923, 2024). "Recurring mutations in genes encoding 3′ splice-site recognition proteins, U2AF1 and ZRSR2 are associated with human cancers." (PMID 38088204, 2024). "We found that double KO EXO1-FANCG and EXO1-ZRSR2 cells are further sensitised by ionising radiation, suggesting that an EXO1-inactivating chemotherapeutic could effectively combine with radiotherapy in the treatment of FA- or ZRSR2-deficient cancers." (PMID 41006228, 2025). "Notably, loss-of-function mutations in ZRSR2 cause widespread minor intron retention and thus enhance hematopoietic stem cell self-renewal as well as drive diverse cancer predisposition, which putatively results from LZTR1 minor intron retention." (PMID 34196950, 2022). "We evaluated 6 splicing factor mutations commonly observed in cancer, including hotspot mutations in SF3B1K700E, U2AF1S34F, and CRISPR-engineered loss of function in FUBP1, RBM5, RBM10, and ZRSR2." (PMID 41279721, 2025). "The most common changes related to cancer in ZRSR2 are missense and synonymous substitutions (~50%), with only 30% resulting in nonsense substitution or frameshift changes that result in ZRSR2 deletion." (PMID 39907312, 2025). "Recent studies on cancer genomes have revealed that recurrent somatic mutations of genes encoding RNA splicing factors (e.g. SF3B1, U2AF1, SRSF2, ZRSR2) lead to altered splice site preferences, resulting in cancer-specific mis-splicing of genes." (PMID 33427197, 2021). "Specifically, we uncover cancer vulnerabilities amongst synthetic lethal hits with EXO1 loss, including deficiencies in BRCA1-A complex factors, FA pathway genes and the splicing factor and tumour suppressor ZRSR2." (PMID 41006228, 2025). "Of note, the tumour suppressors KDM5C and KDM6A have been previously identified to play fundamental roles in cancer sex-disparity, as they escape XCI to retain their function when mutated, while ZRSR2 mutations/loss have been associated with sex-disparity in blood cancers." (PMID 37759468, 2023). "Interestingly, the ZRSR2 gene locus is located close to BRCC3 and FANCB on the X chromosome and is homozygously deleted in 6.63% of all cancers through a LINE-1 element retrotransposition event occurring at Xp22.230,31." (PMID 41006228, 2025). "Notably, we detected aberrant expression of XIST, the essential X-chromosome-inactivation lncRNA that is not normally expressed in males, and upregulation of genes known to escape X-inactivation, including male-biased cancer-related genes KDM6A, DDX3X, KDM5C, and ZRSR2." (PMID 42070154, 2026). "Notably, the treatments altered the gene expression of several tumorigenic and immunologic mediators, including MSXI, ZRSR2, GALNTL6, IL24, and IL18R1, which may impact cancer cell behavior." (PMID 42158898, 2026).
hematological disease (9 papers, 2018 to 2025). "To validate our findings, we analyzed the splicing landscape and expression profiles of key splicing machinery genes, including SRSF2, U2AF1, and ZRSR2, which are known to be frequently mutated in hematological malignancies." (PMID 40158006, 2025). "Although loss-of-function mutations in the ZRSR2 gene frequently occur in hematologic disorders, the exact roles of ZRSR2 in splicing of U2-type and U12-type introns have not been firmly established." (PMID 38088204, 2024). "Since somatic mutations have been frequently found in ZRSR2 gene in hematological malignancies, there is growing interest in better understanding of the functions of U2AF1-relaed factors in splicing of U2-type and U12-type introns." (PMID 38088204, 2024). "Since recurrent ZRSR2 somatic mutations are found in hematological diseases, we investigated the role of Zrsr2 in hematopoiesis ontogeny by WISH with lineage-specific markers for both primitive and definitive hematopoiesis." (PMID 36142581, 2022). "In addition, ZRSR2 mutations are occasionally associated with other hematological diseases, i.e., chronic myelomonocytic leukemia, refractory anemia with ringed sideroblasts, secondary acute myeloid leukemia, and blastic plasmacytoid dendritic cell neoplasm." (PMID 36142581, 2022). "Mutations in splicing factors, such as U2AF1, SF3B1, SRSF2, ZRSR2, and HNRNPH1, are frequently observed across various hematological malignancies and are associated with poor prognosis and treatment resistance." (PMID 39584923, 2024). "Notably, mutations in spliceosomal genes such as SF3B1, U2AF1, SRSF2, ZRSR2, and the RNA-stabilizing methyltransferase METTL3 are specifically enriched in haematological disease." (PMID 40495353, 2025).
tumor (7 papers, 2016 to 2025). "RUNX, ZRSR2, and SF1 have also been reported in MDS; RUNX1 plays an important role in regulating the transcription of many tumor-suppressor genes, while ZRSR2 is an essential component of the splicing machinery, and SF1 is a component of the RNA-splicing machinery." (PMID 27959900, 2016). "Additional genes with tumor suppressor activity were also differentially expressed, such as X-inactivation initiator XIST and ESCAPE splicing factor ZRSR2." (PMID 33527138, 2021). "Mutations in various splicing regulatory factors such as U2AF1, ZRSR2, SRSF2, SF3B1, and RBM10 have been described in multiple tumor types." (PMID 28105922, 2016).
ZRSR2 also shares sentences with these, for which no sentence is quoted: acute myeloid leukemia (7 papers); myeloproliferative neoplasm (2); anemia (1); aplastic anemia (1); blood cancers (1); dysplasia (1); Insulin resistance (1); mastocytosis (1); myelofibrosis (1); neutropenia (1); ovarian carcinoma (1); overlap syndromes (1); polycythemia vera (1); primary myelofibrosis (1); prostate carcinoma (1); Splenomegaly (1); thyroid cancer (1); uveal melanoma (1).